SPINK4 (serine peptidase inhibitor Kazal type 4)
Diseases named in the same sentence as SPINK4 in open-access papers (continued):
Sharing a sentence is not in itself a finding about the gene and the disease.
colitis (1 paper, 2024). Inflammation of the colon. "Therefore, the aim of this study is to investigate the role and underlying mechanisms of SPINK4 in colitis." (PMID 38997284, 2024). "Owing to the abundance of SPINK4 in the intestine, it is a promising candidate for targeted therapy for colitis." (PMID 38997284, 2024). "We also assessed the Spink4 expression in acute and chronic colitis models induced by DSS or 2,4,6-trinitrobenzene sulfonic acid (TNBS)." (PMID 38997284, 2024). "Taken together, the stimulation of SPINK4 production by bacteria-derived Pam2CSK4 promotes epithelial regeneration, particularly the regeneration of GCs during the early stage of colitis." (PMID 38997284, 2024). "Further histological staining was performed, which demonstrated that Pam2CSK4 can alleviate colitis by triggering SPINK4 production and GC remodeling." (PMID 38997284, 2024). "Within SPINK4 deficiency in the epithelium, the expression of phosphorylated EGFR in colitis lesions decreased." (PMID 38997284, 2024). "There was an increased permeability associated with SPINK4 deficiency, not only in the colitis model but also under normal conditions." (PMID 38997284, 2024). "Our group found that SPINK4, a GC secretory factor at an early stage, played an essential role in the development and progression of IBD and colitis models." (PMID 38997284, 2024). "To examine the potential beneficial effect of SPINK4 in IBD, we constructed two colitis animal models and delivered murine rSPINK4 by intraperitoneal injection." (PMID 38997284, 2024). "Our results suggest SPINK4 as a receptor agonist of EGFR targeting the epithelium recovery, and participating in the colitis pathogenesis." (PMID 38997284, 2024). "Our results suggest that SPINK4 participates in the regulation of intestinal regeneration and differentiation by directly influencing the EGFR pathway in colitis." (PMID 38997284, 2024). "Thus, SPINK4 serves as a serologic biomarker of IBD and has therapeutic potential for colitis via intrinsic EGFR activation in intestinal homeostasis." (PMID 38997284, 2024). "In conclusion, we identified SPINK4 as not only a promising biomarker for the identification of IBD and estimation of the specific endoscopic status in colitis but also a target to ameliorate colitis by rebuilding GCs and the mucus layer via EGFR signaling and its downstream effectors." (PMID 38997284, 2024). "The abundance of Spink4 was higher in colitis models than in the controls; however, Spink4 was barely expressed in the active stage and upregulated during remission in the DSS-induced colitis intestine with a significant difference, consistent with GC deficiency." (PMID 38997284, 2024). "The significant decrease in SPINK4 in active stage suggests its potential occurrence during the specific clinical process of acute colitis or the preclinical phase of IBD, particularly UC, which could be attributed to the dramatical depletion of goblet cells during the onset of colitis." (PMID 38997284, 2024). "However, the proliferation potency in cKO colitis mice was diminished even without DSS treatment, consistent with the slightly decreased levels of ISC RNA markers, which might be due to the balance required for intestinal homeostasis supported by endogenous SPINK4." (PMID 38997284, 2024).
dysplasia (1 paper, 2018). A usually neoplastic transformation of the cell, associated with altered architectural tissue patterns. "Specifically, quantification of triple immunofluorescence staining of eight BO EMR specimens with intestinal metaplasia but no dysplasia taken from five patients showed 41% of MUC2 low cells expressed SPINK4 and/or ITLN1, whereas 28% of cells expressed MUC2 alone." (PMID 30323168, 2018). "In 30 BO endoscopic mucosal resection (EMR) specimens (from 16 patients) with intestinal metaplasia but no dysplasia present, we also consistently observed cells expressing ITLN1 or SPINK4 without MUC2." (PMID 30323168, 2018).
hepatocellular carcinoma (1 paper, 2024). A malignant tumor that arises from hepatocytes. "For hepatocellular carcinoma (HCC), we performed a tumor classification using a 4-gene signature (CYP26B1, MCM10, SPINK4, and TRIM54) derived from differentially expressed genes (DEGs) associated with ubiquitination." (PMID 38870259, 2024).
mucinous adenocarcinoma (1 paper, 2023). An invasive adenocarcinoma composed of malignant glandular cells which contain intracytoplasmic mucin. "Our results indicate that mucinous adenocarcinoma cancer cells have goblet cell-like properties, and express high levels of goblet cell markers (REG4, SPINK4, FCGBP and MUC2) compared to classical adenocarcinoma cancer cells." (PMID 36690709, 2023).
prostate tumors (1 paper, 2025). "Prostate tumors that overexpress SPINK4 are frequently resistant to standard treatments, such as ADT." (PMID 40872585, 2025). "SPINK1 and SPINK4 are overexpressed in some aggressive prostate tumors." (PMID 40872585, 2025).
tumor (13 papers, 2019 to 2025). "In conclusion, a detailed analysis of SPINK4 in CRC showed that it is markedly downregulated in tumor tissues and is associated with a poor prognosis." (PMID 38747892, 2024). "The expression of SPINK4 was significantly correlated with not only the tumor mutation burden of THCA, PRAD, STAD, LUAD and ESCA, but also the MSI score of TGCT, STAD, PRAD and KIRC." (PMID 38097680, 2023). "Diagnostic value of SPINK4 and combination with other tumor biomarkers." (PMID 30976466, 2019). "Studies consistently show that SPINK4 mRNA and protein levels are significantly reduced in tumor tissues compared to controls." (PMID 41127012, 2025). "The importance of SPINK4 in previous studies on cancer also lies in its involvement in tumor proliferation, migration, and invasion." (PMID 38747892, 2024). "SPINK4 overexpression significantly reduced tumor volume in vivo, indicating its inhibitory role in carcinogenesis." (PMID 38747892, 2024). "Tumor specimens collected from mice showed that tumor cells overexpressing SPINK4 were significantly smaller in size compared with vehicle controls." (PMID 38747892, 2024). "Functional analysis demonstrates that SPINK4 acts as a tumor suppressor by inhibiting the growth, invasion, and migration of CRC cells and inducing cell cycle arrest in the G1 phase." (PMID 38747892, 2024). "Quantitative analysis of tumor volume further confirmed this observation, with tumors overexpressing SPINK4 significantly reduced in size compared with vehicle controls." (PMID 38747892, 2024). "As a key inhibitor of glycolytic metabolism in CRC, SPINK4 promises metabolic intervention in CRC therapy due to its impact on tumor growth and cell proliferation." (PMID 38747892, 2024). "The results indicated that compared with the NC control group, overexpression of SPINK4 significantly increased tumor size." (PMID 37013514, 2023). "Altogether, our results proved SPINK4 was a tumor suppressor gene by weakening proliferation and migration of tumor cells." (PMID 38097680, 2023). "Then, the functional experiment showed that the silence of SPINK4 promoted the proliferation and migration of cancer cells, suggesting SPINK4 as a tumor suppressor gene." (PMID 38097680, 2023). "SPINK4 may block these processes by inhibiting these proteases, potentially preventing tumor metastasis." (PMID 41127012, 2025). "SPINK4 can reduce the expression of serine proteases with tumor-suppressive properties." (PMID 40872585, 2025). "Inhibiting SPINK4 might potentially reduce CRC cell proliferation and make tumor cells more susceptible to ferroptosis-inducing drugs, enhancing therapy results for CRC patients." (PMID 40872585, 2025). "In the current study, we investigated whether protein expression of REG4, SPINK4 and alpha-1 antitrypsin (A1AT, encoded by SERPINA1) in the tumor associated with CAT in an independent cohort of CRC patients." (PMID 38066386, 2024). "Finally, the impact of SPINK4 overexpression on tumor development was assessed using a xenograft model, while histological and immunohistochemical analyses characterized SPINK4 expression patterns in CRC tissues." (PMID 38747892, 2024). "Besides, the mechanism of SPINK4 in impacting proliferation and migration of tumor cells remains still unclear, so more experiments for confirmation is necessary." (PMID 38097680, 2023). "Moreover, although Erastin treatment decreased tumor size, the overexpression of SPINK4 also significantly promoted tumor size in the presence of Erastin, suggesting that the overexpression of SPINK4 blocked Erastin-induced ferroptosis in vivo." (PMID 37013514, 2023). "Since proteins are secreted by various cells as a response to various stimuli, determining whether serum SPINK4 is directly derived from the tumor needs further research." (PMID 31888570, 2019). "In addition, the differences in SPINK4 expression in other tumor and normal tissues of multiple cancer types were analyzed in the GEPIA database." (PMID 31888570, 2019).
tumor (continued). "By inhibiting the function of these proteases, SPINK4 may increase tumor development and invasion." (PMID 40872585, 2025). "Expression of REG4 and SPINK4 in the tumor may indicate a proinflammatory status of the tumor." (PMID 38066386, 2024). "Additionally, SPINK4 overexpression suppressed subcutaneous xenograft tumor growth in vivo." (PMID 38747892, 2024). "Moreover, we found that SPINK4 was closely related to the level of immune cell infiltration in most tumor types, indicating that SPINK4 played an important role in regulating the immune response within the tumor microenvironment." (PMID 38097680, 2023). "Finally, nude mouse model experiments confirmed that SPINK4 promotes tumor growth and suppresses the ferroptotic effect, demonstrating that SPINK4 may act as an inhibitor of ferroptosis in CRC cells." (PMID 37013514, 2023). "Immunohistochemistry analysis showed that CYP26B1, MCM10, SPINK4, and TRIM54 were highly expressed in tumor tissue compared to normal tissue." (PMID 38870259, 2024). "Tumor tissues exhibited high expression levels of CYP26B1, MCM10, SPINK4, and TRIM54 in the current study." (PMID 38870259, 2024). "Tumor tissues exhibited elevated expression levels of CYP26B1, MCM10, SPINK4, and TRIM54 compared to normal liver tissues, as indicated by the results." (PMID 38870259, 2024). "The results of mouse model further demonstrated that SPINK4 overexpression inhibited CRC cell ferroptosis and facilitated tumor growth." (PMID 37013514, 2023). "Two CRC cell lines (HCT116 and LoVo) were selected, and the in vitro and in vivo experiments showed that overexpression of SPINK4 greatly promotes the proliferation and metastasis of CRC cells and tumor growth (P < 0.05)." (PMID 37013514, 2023). "Subcluster 5, distinctly derived from the tumour tissue, overexpressed mucus secretion‐related genes (CXCL17, TFF3, MUC5AC, SPINK4 and MSMB, etc.)." (PMID 35075805, 2022). "In this study, we found that the serum SPINK4 level was especially increased in preoperative CRC patients and reduced after tumor resection." (PMID 30976466, 2019).
cancer (11 papers, 2019 to 2025). A tumor composed of atypical neoplastic, often pleomorphic cells that invade other tissues. "This resistance might be achieved by SPINK4-induced changes in cellular-signalling pathways that favour survival and proliferation, rendering cancer cells less susceptible to therapy." (PMID 40872585, 2025). "Downregulation of Spink4 (its downregulation known to be associated with poor survival of cancer cells), Ttll9 (involved in microtubule cytoskeleton organization and protein polyglutamylation), and Nppa (has a role in mediating cardio-renal homeostasis) was also observed." (PMID 36130284, 2022). "The ambiguous results of SPINK4 immuno-expression in colorectal tissues with cancer involvement for outcome prediction are presented in distinct studies." (PMID 38997284, 2024). "This multifaceted role emphasizes the key impact of SPINK4 on the invasiveness of cancer cells, further emphasizing its role in oncology research." (PMID 38747892, 2024). "The higher SPINK4 levels are related to the advancement of CRC as they correspond with the site of cancer and distant metastases." (PMID 38747892, 2024). "Pan-cancer analysis revealed that SPINK4 expression was significantly associated with survival, clinical stage, immune score, TMB score and MSI in many other cancer types." (PMID 38097680, 2023). "SPINK4 was mainly located in the cytoplasm and membrane of normal mucosal epithelial cells and primary cancer cells." (PMID 31888570, 2019). "Notably, SPINK4 has led to investigations into its expression levels and regulatory role in cellular processes in cancer research, particularly in CRC." (PMID 38747892, 2024). "In addition to opening up new possibilities for diagnostic and treatment approaches, an understanding of the roles and regulation of SPINK4 offers insightful insights into the molecular mechanisms behind the development and progression of cancer in CRC." (PMID 38747892, 2024). "The results indicated that the expression of SPINK4 was correlated with immune cell infiltration, which indicated that SPINK4 might participate in the occurrence and development of cancers by regulating the recruitment of immune cells." (PMID 38097680, 2023). "Furthermore, at the single-cell level functional analysis in our study, SPINK4 was deregulated in cancer stem cells, which were demonstrated to show a distinct metabolic phenotype that can be highly glycolytic or oxidative phosphorylation-dependent." (PMID 31888570, 2019). "Also, SPINK4 has attracted interest as a biomarker in numerous malignancies, with research confirming its relationship with survival, therapeutic response, and metastasis in pan-cancer analysis." (PMID 40872585, 2025). "Altogether, SPINK4 may serve as a potential drug target for the treatment of cancer patients." (PMID 38097680, 2023). "A pan-cancer analysis showed that SPINK4 was highly expressed in COAD and READ, followed by STAD, LAML, PAAD, PCPG and other cancer types." (PMID 38097680, 2023). "Second, the exertion of SPINK4 function in cancer progression is generally indirect and not straightforward." (PMID 34202399, 2021).
gastrointestinal disease (2 papers, 2019 to 2023). A disease that occurs in the gastrointestinal system, excluding the hepatobiliary system. "Collectively, current studies have demonstrated that aberrant expression of SPINK4 is involved in gastrointestinal diseases." (PMID 37013514, 2023). "Collectively, recent studies demonstrated that SPINK4 was closely related to gastrointestinal diseases, but its role in CRC was largely unknown." (PMID 30976466, 2019).
SPINK4 also shares sentences with these, for which no sentence is quoted: ulcerative colitis (2 papers); adenocarcinoma (1); colon (1); colorectal adenocarcinoma (1); diabetes (1); Hyperinsulinemia (1); infection (1); lung fibrosis (1); lymph node metastasis (1); pancreatic adenocarcinoma (1); Rectal Adenocarcinoma (1); thrombosis (1); thyroid carcinoma (1).